GJB2 (gap junction protein beta 2)
Diseases named in the same sentence as GJB2 in open-access papers (continued):
Sharing a sentence is not in itself a finding about the gene and the disease.
auditory neuropathy (5 papers, 2013 to 2025). A hearing disorder characterized by impaired transmission of signals through the auditory nerve, resulting in mild to severe hearing loss and poor speech perception. "To assess the potential for treating GJB2 and other forms of hereditary hearing loss with ACEMg, we tested the influence of ACEMg on the cochlea and hearing of mouse models for two human mutations: GJB2, the leading cause of childhood deafness, and DIAPH3, a cause of auditory neuropathy." (PMID 26965868, 2016).
breast tumor (5 papers, 2015 to 2021). "Just like the CST2, GJB2, UBE2T, NUF2 and ORC6 also showed the same high expression level in breast tumors." (PMID 31182966, 2019).
pancreatic adenocarcinoma (5 papers, 2014 to 2023). "After validation of a subgroup of DEGs by using an additional pancreatic adenocarcinoma dataset, we found that GJB2 were upregulated and ERO1LB downregulated in malignant tissues than in normal pancreatic tissues." (PMID 28177904, 2017). "For each of the five discovery datasets, GJB2 expression was markedly elevated while ERO1LB expression significantly reduced in pancreatic adenocarcinoma samples than in control samples." (PMID 28177904, 2017). "Finally, the mechanistic role of GJB2 in pancreatic adenocarcinoma (PAAD) was analyzed using the LinkedOmics database." (PMID 37427102, 2023).
squamous cell carcinoma (5 papers, 2005 to 2022). A carcinoma arising from squamous epithelial cells. "It has been reported that these KID patients with germline GJB2 mutation have increased risks of developing epithelial malignancies, for example, 19% occurrence of squamous cell carcinoma of the skin and oral mucosa compared to the normal population." (PMID 32371905, 2020).
thalassemia (5 papers, 2018 to 2025). An inherited blood disorder characterized by a decreased synthesis of one of the polypeptide chains that form hemoglobin. "The most common variants in HL carriers were c.235delC of GJB2, c.919‐2A>G of SLC26A4, and m.1555A>G of MT‐RNR1, and those in thalassemia carriers were ‐SEA, ‐α3.7, and HBB:c.126_129delCTTT." (PMID 39988971, 2025).
cervical carcinoma (4 papers, 2013 to 2022). A carcinoma arising from either the exocervical squamous epithelium or the endocervical glandular epithelium. "Relationships between GJB2 expression and clinical factors in cervical cancer." (PMID 35936685, 2022).
Clouston syndrome (4 papers, 2011 to 2022). Clouston syndrome (or hidrotic ectodermal dysplasia) is characterized by the clinical triad of nail dystrophy, alopecia, and palmoplantar hyperkeratosis. "Four diseases, including clouston syndrome or hidrotic ectodermal dysplasia (HED), have been linked to variants of GJB6, a gene located just 30 kb telomeric to GJB2 on chromosome 13." (PMID 29018324, 2017).
diabetes (4 papers, 2009 to 2024). "Analysis of variants within the family revealed the father to have a homozygous pathogenic variant in the GJB2 gene, which clarified the cause of his hearing loss, and a heterozygous variant in the GCK gene, responsible for GCK-MODY diabetes." (PMID 39766859, 2024). "Among the genes that were significantly up-regulated in diabetes were Retnla, Gjb2, Itga, Slit and Dusp6, and among the genes that were down-regulated were Krueppel-like factor 8, IGFBP, Ngfg, Foxa3, Kcnc2 and Dlp8." (PMID 19649297, 2009).
non-small cell lung carcinoma (4 papers, 2020 to 2023). A group of at least three distinct histological types of lung cancer, including non-small cell squamous cell carcinoma, adenocarcinoma, and large cell carcinoma. "lncRNA CAR10 regulates the expression of gap junction protein beta 2 via miR-892a, thus promoting the migration and invasion capacity of non-small-cell lung cancer cells." (PMID 37925170, 2023).
breast ductal carcinoma (3 papers, 2012 to 2019). "Similarly, upregulation of GJB2 expression, which is involved in local invasion of breast ductal carcinoma, was also found." (PMID 23236365, 2012).
cataract (3 papers, 2016 to 2025). Partial or complete opacity of the crystalline lens of one or both eyes that decreases visual acuity and eventually results in blindness. "Variants in GJA3 have been associated with cataracts in humans, while mutations in GJB2 and GJB6, encoding for connexin-26 and 30, respectively, transmembrane proteins involved in the formation of gap junction in the cochlea, are known for their critical roles in hearing." (PMID 40025542, 2025).
congenital adrenal hyperplasia (3 papers, 2022 to 2024). Congenital adrenal hyperplasia (CAH) is an inherited endocrine disorder caused by a steroidogenic enzyme deficiency that is characterized by adrenal insufficiency and variable degrees of hyper or hypo androgyny manifestations, depending of the type and the severity of the disease. "GJB2-related non-syndromic hearing loss with a frequency of 3.7% was the most common autosomal recessive disease, followed by congenital adrenal hyperplasia (CAH) (2.9%) and hepatolenticular degeneration (2.6%)." (PMID 35079019, 2022).
Wilson disease (3 papers, 2022 to 2025). A very rare inherited multisystemic disease presenting non-specific neurological, hepatic, psychiatric or osseo-muscular manifestations due to excessive copper deposition in the body. "In this couple, the woman was first screened as an extensibility carrier for 15 genetic diseases, and the results showed that she was a carrier of the pathogenic genes ATP7B and GJB2 for Wilson’s disease and hereditary deafness, respectively." (PMID 37031186, 2023). "The common mutation spectrum of GJB2 and SLC26A4 in this study was consistent with previous literature reports of the Chinese population, while the mutation spectrum of ATP7B was inconsistent with a research report of Chinese patients with Wilson's disease." (PMID 37031186, 2023).
acute myeloblastic leukemia (2 papers, 2021 to 2025). "GJB2 has been found a supportive role as a junction protein in acute myeloid leukemia, potentially linked to development and chemotherapy sensitivity." (PMID 40308607, 2025).
cholesteatoma (2 papers, 2012 to 2015). A pathologic process characterized by the proliferation of keratinizing squamous epithelium resulting in the accumulation of keratin and cells in the middle ear and/or mastoid. "Real-time PCR of PI3, SPRR1B, LCN2 (lipocalin 2), MMP1, MMP9, MMP10, MMP12, SPP1, GJB2, Bcl-xl (BCL2L1), cIAP2 (BIRC3), S100A7A (koebnerisin), S100A9, SERPINB3, CEACAM6, KRT6B and SERPINB4 revealed that the expression levels of these proteins were higher in cholesteatoma than in external canal skin." (PMID 23285167, 2012).
congenital sensorineural deafness (2 papers, 2024 to 2025). "GJB2 encodes the gap junction protein Connexin-26 (CX26) on chromosome 13q12.11, which variants and causes congenital sensorineural deafness." (PMID 39754783, 2025).
cytomegalovirus infection (2 papers, 2020 to 2023). A herpesvirus infection caused by Cytomegalovirus. "Our study has several limitations, such as the sparsity of data from low-income countries and insufficient data on the causes of congenital hearing loss, such as mutations in GJB2, congenital cytomegalovirus infection, and congenital rubella infection." (PMID 37824170, 2023).
erythrokeratoderma (2 papers, 2022 to 2023). An umbrella term for a group of rare genetic skin disorders characterized by well-demarcated plaques of reddened, dry and thickened skin. "At the beginning, Netherton syndrome and Erythrokeratoderma variabilis phenotypes were suspected, but no hair shaft abnormalities were found and no mutations in SPINK5 and EKV genes (GJB2, GJB3, GJB4, GJB6 and KDSR) were identified (data not shown)." (PMID 34983512, 2022).
gastric cancer (2 papers, 2015 to 2023). A primary or metastatic malignant neoplasm involving the stomach. "In our study, GEPIA and KM plotter database analysis showed that high GJB2 expression was associated with good prognosis outcomes in patients with gastric cancer." (PMID 37427102, 2023). "Previous studies have also reported contradictory findings regarding the correlation between GJB2 expression and the prognosis of gastric cancer patients." (PMID 37427102, 2023). "In the future, comprehensive clinical studies are required to further validate the correlation between gastric cancer prognosis and GJB2 expression.Our data also showed that high expression of GJB2 was associated with worse prognosis outcomes in patients with CESC, KIRC, OV, GBM, and SARC." (PMID 37427102, 2023).
Meniere disease (2 papers, 2008 to 2020). A disease of the inner ear (labyrinth) that is characterized by fluctuating sensorineural hearing loss; tinnitus; episodic vertigo; and aural fullness. "A recent report showed that rare variants within the coding region of GJB2 gene and other HI genes are associated with Meniere disease (MD)." (PMID 33126609, 2020).
meningitis (2 papers, 2022 to 2025). A disorder characterized by acute inflammation of the meninges of the brain and/or spinal cord. "35.2% of the cases were connected to the pathogenic mutations of the GJB2 gene, the other reasons were meningitis, cytomegalovirus or other intrauterine infections, premature, hypoxia, ototoxic medication, neurodegenerative disorders, hyperbilirubinaemia, long NICU stay." (PMID 35767058, 2022).
osteosarcoma (2 papers, 2020 to 2025). A usually aggressive malignant bone-forming mesenchymal neoplasm, predominantly affecting adolescents and young adults. "Our second representative case was a female patient with osteosarcoma, diagnosed at 10, who carried a pathogenic variant in GJB2 in addition to a germline duplication of DDX10, the latter, a known marker somatically associated with poor prognosis for osteosarcoma." (PMID 32371905, 2020).
ovarian carcinoma (2 papers, 2019 to 2023). A malignant neoplasm originating from the surface ovarian epithelium. "Cancer- associated fibroblasts showed positive correlation with GJB2 expression in most tumors, with the strongest positive correlation in ovarian cancer." (PMID 37427102, 2023). "Expression levels of GJB2, S100A2 and SPOCK2 were increased in ovarian cancer and their upregulation was linked to poor prognosis of patients with ovarian cancer." (PMID 31794425, 2019). "Subsequently, we introduced the ovarian cancer data other than TCGA to further assess the survival effects of GJB2, S100A2, SPOCK2 and TGM1 on prognosis (OS) by Kaplan-Meier plotter." (PMID 31794425, 2019). "Ovarian cancer patients with higher expression of GJB2, S100A2 and SPOCK2 showed better OS, which was identical with the analytic results obtained from TCGA cohort." (PMID 31794425, 2019). "Taken together, GJB2, S100A2 and SPOCK2 might be three key genes in mediating tumor stage progression of ovarian cancer and causing poor prognosis." (PMID 31794425, 2019). "Among all the predicted miRNAs of GJB2, high expression of hsa-miR-522-3p and hsa-miR-105-5p indicated favorable OS of patients with ovarian cancer but hsa-miR-485-5p was an unfavorable prognostic biomarker for ovarian cancer." (PMID 31794425, 2019). "In this study, based on comprehensive expression analysis and survival analysis, three genes (GJB2, S100A2 and SPOCK2) were identified as key genes which may be associated with progression of ovarian cancer." (PMID 31794425, 2019). "High expression of GJB2, S100A2, SPOCK2, TGM1or EPS8 indicated a poor OS of patients with ovarian cancer, whereas ovarian cancer patients with higher expression of ADAMDEC1, CHEK1, EGFL6, FAM181A, FOXA2, LYPD1, PART1 or XPR1 possessed better OS." (PMID 31794425, 2019). "All these reports together with our current analytic results of expression and survival analysis demonstrate that GJB2, S100A2 and SPOCK2 may be three key oncogenes in the progression of ovarian cancer." (PMID 31794425, 2019).
retinitis pigmentosa (2 papers, 2023 to 2024). Retinitis pigmentosa (RP) is an inherited retinal dystrophy leading to progressive loss of the photoreceptors and retinal pigment epithelium and resulting in blindness usually after several decades. "Indeed, Patient 46 presents GJB2-associated HL and RPGR-associated retinitis pigmentosa while Patient 50 is affected by WFS1-related HL and pseudoxanthoma elasticum due to an ABCC6 mutation." (PMID 36979683, 2023).
sarcoma (2 papers, 2015 to 2023). A usually aggressive malignant neoplasm of the soft tissue or bone. "EWSR1-WT1-regulated genes expressed more highly in recurrent than primary DSRCT included GJB2, GAL, and GALP, which were recently identified as highly enriched in DSRCT compared to other sarcoma types." (PMID 37457440, 2023).
sudden hearing loss (2 papers, 2021 to 2025). "In our group, we once screened the GJB2 gene in 93 sudden hearing loss patients and 117 controls with normal hearing." (PMID 33718389, 2021). "In patients with idiopathic hearing loss and sudden sensorineural hearing loss, although not as high as patients with genetic variations of GJB2, SCL26A4, and LMX1A, the ratios of EH detected in HYDROPS MRI was relatively high, reaching 20–40%." (PMID 39373914, 2025).
Usher syndrome type 1 (2 papers, 2014 to 2025). A syndrome characterized by congenital, bilateral, severe sensorineural hearing loss, abnormalities in the vestibular system, and adolescent-onset retinitis pigmentosa. "In particular, from the prognostic perspective, we can expect successful results of CI in hereditary deafness with mutation of specific genes, such as, GJB2, SLC26A4, mitochondrial mutations, OTOF, Usher syndrome type I, DFNA9 (COCH), and DFNA17 (MYH9)." (PMID 25373420, 2014).
X-linked disease (2 papers, 2022 to 2024). X-linked form of disease. "The most prevalent genes were GJB2 for autosomal recessive disorders and G6PD for X-linked diseases." (PMID 36072675, 2022).
AIDS (1 paper, 2025). A syndrome resulting from the acquired deficiency of cellular immunity caused by the human immunodeficiency virus (HIV). "The reduction in GJB2 levels was inversely correlated with increased HIV-1 infection levels, suggesting the potential of GJB2 for combating HIV/AIDS." (PMID 40980890, 2025). "Importantly, when we reintroduced GJB2 into CD4+ T cells isolated from anti-retroviral therapy (ART)-treated patients, we observed that GJB2 overexpression still inhibited HIV-1 spread in these cells ex vivo, suggesting a potential application for combating HIV/AIDS." (PMID 40980890, 2025).
aniridia (1 paper, 2022). Aniridia is a congenital ocular malformation characterized by the complete or partial absence of the iris. "The ECS results showed that they were classified as ARC for GJB2, whereas the female partner had a P variant of autosomal dominant condition PAX6 related to aniridia." (PMID 36072675, 2022).
Becker muscular dystrophy (1 paper, 2025). Becker muscular dystrophy (BMD) is a neuromuscular disease characterized by progressive muscle wasting and weakness due to degeneration of skeletal, smooth and cardiac muscle. "In 5 couples, both partners have P/LP variants in the same AR gene (CFTR, GJB2, ATP7B, DHCR7), and in one couple, a woman has a clinically significant variant in the DMD gene linked to Becker muscular dystrophy." (PMID 41595422, 2025).
CHARGE syndrome (1 paper, 2023). CHARGE syndrome is a multiple congenital anomaly syndrome characterized by the variable combination of multiple anomalies, mainly Coloboma; Choanal atresia/stenosis; Cranial nerve dysfunction; Characteristic ear anomalies (known as the major 4 C's). "GJB2-associated uSNHL and CHARGE syndrome have previously been diagnosed in retrospective studies of uSNHL in children." (PMID 36675424, 2023).
dimethylglycine dehydrogenase deficiency (1 paper, 2023). An extremely rare autosomal recessive glycine metabolism disorder characterized clinically in the single reported case to date by muscle fatigue and a fish-like odor. "However, the GCR of DMGDH, CD36 and GJB2, the variants on which were linked to diseases Dimethylglycine dehydrogenase deficiency, Platelet glycoprotein IV deficiency, and Deafness (autosomal recessive 1A), respectively, exhibited substantial variations across ethnic groups." (PMID 37985665, 2023).
dysentery (1 paper, 2020). Acute inflammation of the intestine associated with infectious diarrhea of various etiologies, generally acquired by eating contaminated food containing toxins, biological derived from bacteria or other microorganisms. "Dysentery has been endemic at least since the advent of urbanization, and resistance to this disease via altered connexons may have provided enough positive selection to bring the commonest GJB2 mutations to their present frequencies." (PMID 33147256, 2020).
ear malformation (1 paper, 2026). "We assessed the diagnostic performance of a comprehensive 218-gene HL panel in 99 Brazilian probands (78 non-syndromic; 21 syndromic) who had previously tested negative for GJB2/GJB6 (DFNB1) and MT-RNR1 (m.1555A>G) and did not have ear malformations." (PMID 42233699, 2026).
familial cancer (1 paper, 2023). "The frequencies of several detrimental variants of cancer‐related genes (such as GJB2 and SLC25A13) were higher in the non‐familial cancer group than the familial cancer group." (PMID 35861108, 2023).
gastrointestinal infections (1 paper, 2016). "The GJB2 heterozygote advantage might consist of increased resistance to gastrointestinal infections due to the epithelial barrier thickening, as suggested in previous studies." (PMID 27224056, 2016).
genetic non-syndromic hearing loss (1 paper, 2021). "GJB2, which encodes the gap junction protein Connexin 26, is the most common cause of genetic non-syndromic hearing loss (NSHL)." (PMID 33718389, 2021).
hidradenitis suppurativa (1 paper, 2024). A chronic suppurative and cicatricial disease of the apocrine glands occurring chiefly in the axillae in women and in the groin and anal regions in men. "Variants involved the TLR2 and MPO genes in the first family and the MMP2, GJB2, and TLR4 genes, some of which have already been previously reported as possible candidates for hidradenitis suppurativa." (PMID 39595064, 2024).